RET (ret proto-oncogene)
Diseases named in the same sentence as RET in open-access papers (continued):
Sharing a sentence is not in itself a finding about the gene and the disease.
cancer (continued). "Selpercatinib, a highly selective RET-specific inhibitor, demonstrated potent activity in preclinical studies against human cancer cell lines harbouring endogenous RET gene alterations." (PMID 37835559, 2023). "Prospective basket trials and retrospective reports have demonstrated the activity of these drugs in a wide variety of RET-altered cancers, notably those with RET fusions." (PMID 37627175, 2023). "Functions of RET seem to be mainly involved in development, metabolic diseases and cancer, therefore it is difficult to conclude a role during infection by N. meningitidis at the BCSFB." (PMID 37065199, 2023). "BRAF mutations are commonly associated with RET/PTC rearrangement and other frequently occurring genetic mutations, and are thought to play an independent role in the development of cancer." (PMID 37370792, 2023). "Recommendations are provided on the basis of a literature review and the expertise of our group in managing more than 100 patients with RET-altered cancers who were treated with selective RET inhibitors." (PMID 38118420, 2023). "This is also associated with an enhanced transcription of CIITA and consequently of MHC class II expression in the papillary thyroid carcinoma cells, thereby explaining the increased immune cell infiltration of RET/PTC-positive cancers." (PMID 37047709, 2023). "In the cancers with BRAF mutations in our cohort, 50% were metastatic, whereas the ones with RET fusions were largely metastatic (80%)." (PMID 37317665, 2023). "Here, we report the comprehensive molecular portfolio of RET-altered cancers among 523 patients with NSCLC and 368 patients with other solid tumors (excluding NSCLC)." (PMID 36690680, 2023). "As in adults, more aggressive cancer behavior is expected in cases harboring p.V600E or other BRAF point mutations or BRAF-like fusions (e.g., RET/PTC1, NTRK3/ETV6, ALK rearrangements), although these correlations remain unconfirmed in children." (PMID 37046700, 2023). "Additional efforts should lie in exploring the therapeutic potential of these newer-generation TKIs across different cancer types and defining the spectrum of RET alterations." (PMID 37627175, 2023). "Targeted therapies for RET-dependent cancers have evolved from older multikinase inhibitors to selective inhibitors of RET such as selpercatinib and pralsetinib." (PMID 37627175, 2023). "Among these potential druggable alterations, EGFR, KRAS, and PIK3CA gene alterations were the most common, while CDK pathway (CDK4/6, CDKN2A/2B), FGFR1/2/3, BRAF, RET was uncommon across pan-cancer." (PMID 36910668, 2023). "Now, thousands of patients with RET-altered cancers have benefited from first-generation SRIs, with impressive deep and durable responses." (PMID 38201460, 2023). "The main challenge with co-managing COVID-19 and RET-altered cancers is the potential for drug-drug interactions between treatment regimens of both diseases." (PMID 38118420, 2023). "In particular, about 30% of pediatric cancers harbor BRAF/RAS mutations, while gene fusions are present in up to 60% of cases, mainly in younger patients with PTC, usually involving RET or NTRK1/3, as also ALK, BRAF and PPARG." (PMID 37046700, 2023). "The activity of cabozantinib as a RET-directed therapy is less characterized in additional cancer sites, such as patients with RET fusion-positive PTC." (PMID 37627175, 2023). "RET-mediated signaling activates multiple intracellular pathways influencing processes which are critically dysfunctional in cancer, including mitosis, angiogenesis, and motility." (PMID 36918928, 2023). "The RET proto-oncogene codes for a transmembrane protein kinase can spur the growth of cancer cells when it is the activated product of a gene altered through gene fusion or mutation." (PMID 37277734, 2023). "SLP exhibit better results for patients with RET fusion-positive cancer due to better potency and fewer side effects." (PMID 36985590, 2023).
cancer (continued). "The most notable protein kinases involved in fusions include the MAST kinases in breast cancer, present in 3 to 5% of cases, as well as RET in various cancers (particularly lung and thyroid) and other RTKs in a variety of tumors." (PMID 37509339, 2023). "Our data indicated that pathologists experience difficulties in key clinical areas and perceive that there are systems-level barriers to optimal care for patients with RET-altered cancers." (PMID 37277734, 2023). "The NCCN and ATA guidelines suggest dabrafenib plus trametinib for BRAF V600 mutated carcinoma, larotrectinib or entrectinib if NTRK gene fusion is positive and pralsetinib or selpercatinib for RET-fusion positive ATC." (PMID 37076888, 2023). "Multifocality was detected in 48.2% of RET fusion-positive carcinomas, which was significantly higher than in our BRAF V600E and RAS-mutated PTCs." (PMID 37882481, 2023). "RET fusion-positive carcinomas were associated with aggressive disease, including frequent LNM and DM, especially in cases of NCOA4/RET-positive carcinomas, even in early-stage disease, and with increased rates in pediatric and adolescent patients." (PMID 37882481, 2023). "The overall response rate according to RECIST version 1.1 per investigator assessment was 67% and 58% in the RET fusion-positive and RET-mutant cancers, respectively." (PMID 35304457, 2022). "This section of the review will discuss oncogenic RET alterations and their implications in RET-altered cancers." (PMID 35957881, 2022). "The results of the phase 1/2 LIBRETTO-001 clinical trial has recently established the efficacy of the RET inhibitor selpercatinib in RET-driven cancers." (PMID 35304457, 2022). "RET alterations occur in less than 5% of all cancer patients, however activating RET alterations, such as genetic amplification and chromosomal rearrangements, are found in increasingly higher proportions of specific cancer types." (PMID 35957881, 2022). "Here, we show that RET protein is expressed during lactation and abnormal RET expression negatively impacts the post-lactation transition, inducing early markers of cancer." (PMID 35044452, 2022). "The most frequent breakpoints across all cancers took place in RET intron 11, resulting in a fusion product involving RET exon 12 (overall rate, 78.9%, 235/298)." (PMID 36369474, 2022). "Next-generation sequencing targeting 520 cancer-related genes was performed on the pleural effusion samples and revealed 2 novel RET fusions LINCO1264-RET and SEMA5A-RET, concomitant with a common CCDC6-RET." (PMID 36451418, 2022). "TPX-0046, a potent RET/SRC inhibitor, showed antitumor potency against RET G810 solvent front mutation cancer models." (PMID 36508072, 2022). "When evaluated for mutation, 77.7% of cancers had BRAF V600E; 8.8% showed RET/PTC rearrangements; 4.4% were positive for PAX8/PPAr gamma and 9.1% had RAS mutations (H- and K-, no NRAS mutations were found in our series)." (PMID 34350538, 2022). "GFRα serves as a coreceptor with RET on the surface of cancer cells to activate downstream signaling, cancer cell migration, and PNI." (PMID 35582425, 2022). "The latest NSCLC guideline 2021 V2 edition issued by the national comprehensive cancer network (NCCN) indicated that genes associated with targeted therapy of NSCLC include EGFR, KRAS, ALK, ROS1, MET, BRAF, RET, and NTRK." (PMID 35227278, 2022). "Despite substantial experimental effort, we were unable to establish a primary cell line, organoid model, or xenograft in immunocompromised mice; therefore we used established cancer cell lines harboring RET rearrangements to model drug resistance." (PMID 35510953, 2022). "Among these, six cancers had additional genetic alterations: BRAF fusions (n = 2), and one each with RET fusion plus BRCA2 loss of function mutation, IDH1 mutation, RAF1 fusion, and EML4-NTRK3 fusion." (PMID 36124727, 2022). "Rearrangement during transfection (RET) is a widely known proto-oncogene that drives various cancers." (PMID 36557971, 2022).
cancer (continued). "The pivotal clinical trial named Arrow is a global phase I/II clinical trial of pralsetinib (NCT03037385) in RET-related cancers." (PMID 36557971, 2022). "This review will summarize the current understanding of canonical RET signaling and its biology, the role of RET signaling in critical developmental processes, and the oncogenic role of aberrant RET activity in multiple cancer types." (PMID 35957881, 2022). "Thirty‐four amino acid residues in EGFR, ALK, ROS1, RET, NTRK1, and MET proteins contained secondary/tertiary mutations and were reproducibly identified in clinical samples obtained from NSCLCs (and other type of cancers for RET/NTRK fusions)." (PMID 34997674, 2022). "These activities were comparable,and in some cases improved, to those of promiscuous RET inhibitorvandetanib, the standard of care for RET driven cancers." (PMID 36153960, 2022). "We highlighted how, especially in sporadic MTC, new gene alterations involving both RET and other cancer-related genes are emerging alongside the well-known RET and RAS mutations, suggesting a more complex mutational landscape than previously thought." (PMID 35454858, 2022). "Rearrangements involving ALK, ROS1, NTRK family genes, and RET are found in lung, colon, thyroid, and other cancers." (PMID 35510953, 2022). "RET gene abnormalities were shown to be one of the driving alterations in quite a few diseases, including cancers." (PMID 36358717, 2022). "In this article, we review recent targeted drugs, including RET-altered cancer, and raise issues that require further study." (PMID 36557971, 2022). "Elevation in circulating GDF15 correlates with cancer cachexia and GDF15-induced weight loss in mice was reported to be mainly mediated by a GDNF family receptor alpha like (GFRAL)-Ret proto-oncogene (RET) signaling complex in brainstem neurons." (PMID 35379793, 2022). "Collectively, the pattern of resistance observed in RET-driven tumors demonstrates the intrinsic MAPK dependence of RET-altered cancers." (PMID 35304457, 2022). "Taken together, these results indicate that selpercatinib elicits durable efficacy, including intracranial activity, with primarily low-grade toxicity effects in patients with RET-altered cancers." (PMID 35957881, 2022). "In the past few years, cancers with RET alterations have been treated with multikinase inhibitors (MKIs)." (PMID 36557971, 2022). "Considering the potential benefit of treating tumors with RET inhibitors, it is crucial to understand the real impact of these deletions in cancer development and progression and their response to RET targeted therapies." (PMID 36091144, 2022). "Over the last three decades, cumulative studies have established an important role that RET plays in multiple cancer types." (PMID 35957881, 2022). "Collectively, this work links RET kinase as a key regulator of mutant promoter-driven hTERT expression and proposes a novel potential precision medicine strategy for cancer patients harboring mutant hTERT promoter sites." (PMID 36142729, 2022). "Genetic variants of unclear significance were however detected in genes such as CDH1, DICER1, MEN1, RET, CREBBP, RAD51C, or SOS1, which are linked to autosomal dominant predisposition to cancer." (PMID 35250968, 2022). "We found that new gene alterations are emerging, along with the known RET/RAS drivers, involving not only RET by multiple concurrent mutations or deletions but also other previously underestimated cancer-related genes, especially in sporadic MTCs." (PMID 35454858, 2022). "MKIs, selpercatinib, and pralsetinib showed favorable ORRs and OS rates in RET-altered cancer, but the current challenge for RET precision medicine should be solved as quickly as possible." (PMID 36557971, 2022). "This section of the review will briefly summarize the role of RET signaling in other solid tumor types and the implications of RET inhibition in these cancers." (PMID 35957881, 2022).
cancer (continued). "Despite efforts to develop super-selective inhibitors, data available on the response of cancers harboring RET deletions to selective RET inhibitors are scarce and concern only MTCs." (PMID 36091144, 2022). "In vitro studies reveal that selpercatinib selectively inhibits both wild-type and altered RET, spares KDR/VEGFR2 activity, and selectively targets RET-altered cancer cells." (PMID 35957881, 2022). "Understanding the mechanisms of drug resistance in the treatment of RET-dependent cancers is critically important." (PMID 35510953, 2022). "The efficacy of the highly selective RET inhibitor selpercatinib is now established in RET-driven cancers, and we sought to characterize the molecular determinants of response and resistance." (PMID 35304457, 2022). "In support of “inflammation-induced carcinoma”, RET/PTC oncogene has been known to induce a proinflammatory transcriptional program." (PMID 35255870, 2022). "Activity of MKIs in RET fusion-positive NSCLC has been reported in pre-clinical cancer models, in retrospective case series and in phase I and phase II trials." (PMID 33806299, 2021). "Novel potent and VEGFR-sparing TKIs (pralsetinib and selpercatinib) have been identified and demonstrated substantial clinical efficacy in RET-driven cancers; both have been approved as RET-targeted cancer drugs." (PMID 34373541, 2021). "A phase I/II clinical trial for RET inhibitor-resistant and naïve RET-driven cancers is ongoing (NCT04161391)." (PMID 34238332, 2021). "Similar to ALK, another oncogenic RTK, RET, also undergoes multiple distinct and recurrent gene rearrangements in human cancer, leading to the elimination of the extracellular and transmembrane domains from the various fusion oncoproteins." (PMID 33848463, 2021). "In that study, we demonstrated that the anti-cancer mechanism of action of datelliptium involves stabilization of a G-quadruplex structure on the RET promoter region, leading to RET downregulation." (PMID 34209165, 2021). "Until recently, some multikinase inhibitors (MKIs) with nonselective RET-inhibitory activity have been available for patients with RET-altered cancers." (PMID 34832869, 2021). "Driver mutations, including RET, CBL, and DDR2 gene mutations, were identified in the hypermutated cancers." (PMID 34503126, 2021). "Our previous study validated the RET promoter G-quadruplex as a potential target for new anti-cancer therapies against advanced and metastatic MTC." (PMID 34209165, 2021). "An analysis of over 32,000 plasma samples collected from advanced cancer patients was performed to elucidate the co-occurring RET alterations oncogenic signaling pathways identified in liquid biopsy." (PMID 33771190, 2021). "These agents have been developed against a variety of target-kinases other than (or in addition to) RET, such as VEGF receptors, AXL, FGFR1, EGFR, MET, c-KIT and BRAF, and unfortunately demonstrated limited potency for RET-positive cancers." (PMID 33806299, 2021). "The statistical analysis of the data showed a significant difference in the expression of RET in cancer samples in comparison to the normal adjacent samples (P<0.002)." (PMID 33906292, 2021). "Here, we tested Pz-1 anti-neoplastic activity in relevant (thyroid, NSCLC, and CRC) human RET or TRKA-driven cancer models." (PMID 34373541, 2021). "Among patients with RET- cancers, carboplatin + paclitaxel was used among 8.7%, pembrolizumab among 7.6%, and erlotinib among 7.1%." (PMID 33402119, 2021). "Both pralsetinib and selpercatinib have excellent clinical activity in RET-altered cancers conferring deep and durable responses leading to their FDA approval." (PMID 34099825, 2021). "Fusion proteins containing the RTK rearranged during transfection (RET) have been reported in multiple cancer types." (PMID 34068954, 2021). "This study was the largest cancer cohort with somatic activating RET alterations and found that non-KIF5B-RET fusions contributed to anti-EGFR therapy resistance." (PMID 33771190, 2021).
cancer (continued). "As a control, human cancer cell lines of the same tissues but harbouring oncogenes other than RET or TRKA were used." (PMID 34373541, 2021). "A number of RET kinase inhibitors have been approved by the FDA for the treatment of cancer, such as cabozantinib, vandetanib, lenvatinib, and sorafenib." (PMID 33525725, 2021). "The robust response produced by selpercatinib and pralsetinib will benefit patients with RET-mutant cancers." (PMID 33419162, 2021). "In cell-based assays, Pz-1 selectively inhibited, in the low nM range, proliferation of cancer cell lines only when positive for RET or TRK-derived oncogenes, with negligible effects in cells carrying different driver oncogenes (RAS, BRAF, EGFR)." (PMID 34373541, 2021). "Since RET is a crucial therapeutic target in cancers, several multi-kinase inhibitors (MKIs) such as cabozantinib, vandetanib, alectinib, and apatinib have shown anti-RET activities." (PMID 34508169, 2021). "Lenvatinib also inhibits PDGFR alpha, stem cell factor receptor (KIT), and RET, receptor tyrosine kinases that have been reported to be involved in cancer progression." (PMID 34176067, 2021). "Among these oncogenic signaling pathways, the mitogen-activated protein kinase (MAPK) cascade pathway and RET signaling are critical for human cancer cell proliferation, dissemination, and resistance to drug therapy." (PMID 34930913, 2021). "Selpercatinib5–7 and pralsetinib are potent and selective RET TKIs recently approved by the United States Food and Drug Administration as RET-targeted cancer drugs." (PMID 34099825, 2021). "US10030005B2 discloses pyrazole based RET inhibitors and their pharmaceutical compositions to treat a condition mediated by aberrant RET activity, e.g., cancer." (PMID 34451807, 2021). "Somatic RET mutations has been reported in about 25–45% cases of sporadic medullary thyroid carcinoma (MTC), a type of carcinoma with neuroendocrine differentiation." (PMID 33802174, 2021). "The production of matrix proteins via RET activation has been better characterised in the context of cancer." (PMID 33020210, 2020). "Hereditary PCC accounts for ~35% of cases and has been associated with germline mutations in several cancer susceptibility genes (e.g., KIF1B, SDHB, VHL, SDHD, RET)." (PMID 32354376, 2020). "Activating alterations of the RET kinase are therapeutically actionable oncogenic drivers across a variety of cancers, but the role of RET in hematologic malignancies is less well defined." (PMID 32629802, 2020). "From 2002 to 2020, at our cancer genetics clinic, RET genetic testing was performed in 163 subjects (102 complete gene analyses and 61 targeted analyses), 72 of whom presented with MTC." (PMID 33167350, 2020). "Studies regarding RET continue to provide fascinating challenges in the fields of cancer research, neuroscience, and developmental biology." (PMID 33150251, 2020). "Clinical features of RET-dependent cancers and extensive data on RET expression in different tumor types are reviewed elsewhere." (PMID 32993133, 2020). "Before any selective RET inhibitor becomes available, chemotherapy, multi-targeted TKIs, and clinical trials are common choices for RET-altered cancer patients." (PMID 33109256, 2020). "Accordingly, a phase 1/2 clinical study of the multi-targeted RET and SRC kinase inhibitor TPX-0046 (NCT04161391), is ongoing for TKI-naive and TKI-pretreated patients with RET-altered lung, thyroid and other cancers." (PMID 33318047, 2020). "Previously, we developed RET-transgenic mice (RET-mice) carrying oncogenic RET in which hyperpigmented skin and skin benign and malignant tumors developed." (PMID 32460744, 2020).